VAMP7 (vesicle associated membrane protein 7)
Description:
Involved in the targeting and/or fusion of transport vesicles to their target membrane during transport of proteins from the early endosome to the lysosome. Required for heterotypic fusion of late endosomes with lysosomes and homotypic lysosomal fusion. Required for calcium regulated lysosomal exocytosis. Involved in the export of chylomicrons from the endoplasmic reticulum to the cis Golgi. Required for exocytosis of mediators during eosinophil and neutrophil degranulation, and target cell killing by natural killer cells. Required for focal exocytosis of late endocytic vesicles during phagosome formation.
Synonyms: VAMP-7; Ti-VAMP; SYBL1; TIVAMP
Tractability: Antibody: its Gene Ontology location is reachable by antibodies, with high confidence; UniProt predicts a signal peptide or a membrane-spanning region. PROTAC: ubiquitination databases record sites on it; its protein half-life has been measured.
Gene: Protein-coding gene on chromosome X (155,881,227 to 155,943,769, forward strand). Ensembl gene ENSG00000124333.
Subcellular location: Cytoplasmic vesicle, secretory vesicle membrane; Golgi apparatus, trans-Golgi network membrane; Late endosome membrane; Lysosome membrane; Endoplasmic reticulum membrane; Cytoplasmic vesicle, phagosome membrane; Synapse, synaptosome
Subcellular location (Human Protein Atlas): Vesicles
Pathways (Reactome):
Vesicle-mediated transport: Cargo recognition for clathrin-mediated endocytosis; Clathrin-mediated endocytosis; Golgi Associated Vesicle Biogenesis; Lysosome Vesicle Biogenesis; trans-Golgi Network Vesicle Budding
Immune System: Interleukin-12 signaling
Gene Ontology:
Molecular function: protein binding; SNAP receptor activity; SNARE binding
Biological process: autophagosome maturation; endosome to lysosome transport; eosinophil degranulation; natural killer cell degranulation; neutrophil degranulation; positive regulation of histamine secretion by mast cell; vesicle fusion; vesicle-mediated transport; calcium-ion regulated exocytosis; cellular response to starvation; endoplasmic reticulum to Golgi vesicle-mediated transport; exocytosis; macroautophagy; phagocytosis, engulfment
Cellular component: azurophil granule membrane; cytoplasm; extracellular exosome; lamellipodium; lysosomal membrane; membrane; plasma membrane; platelet alpha granule; pseudopodium; secretory granule; secretory granule membrane; SNARE complex; trans-Golgi network; autophagosome membrane; clathrin-coated endocytic vesicle membrane; endoplasmic reticulum membrane; late endosome membrane; neuron projection; phagocytic vesicle; cytoplasmic vesicle; endomembrane system; Golgi apparatus; phagocytic vesicle membrane; plasma membrane bounded cell projection; synapse; and 1 more
Homologues: Orthologues: rat Vamp7 (95% identical), guinea pig VAMP7 (94% identical), tropical clawed frog vamp7 (92% identical), zebrafish sybl1 (83% identical), dog VAMP7 (82% identical), pig VAMP7 (70% identical), chimpanzee VAMP7 (70% identical), macaque VAMP7 (70% identical), Drosophila melanogaster Vamp7 (52% identical), Caenorhabditis elegans snb-5 (8% identical), Caenorhabditis elegans snb-7 (8% identical), Caenorhabditis elegans snb-6 (7% identical). Paralogues in human: VAMP2 (19% identical), YKT6 (18% identical), VAMP4 (17% identical), VAMP1 (16% identical), VAMP8 (15% identical), SEC22B (15% identical), VAMP3 (15% identical), SEC22A (11% identical), SEC22C (11% identical), VAMP5 (11% identical).